INS (insulin)
Diseases named in the same sentence as INS in open-access papers (continued):
Sharing a sentence is not in itself a finding about the gene and the disease.
diabetes (continued). "A total of 86 adults were enrolled into the Livongo for Diabetes program, with 49% (42/86) female, an average age of 50 (SD 15) years, 56% (48/86) with type 2 diabetes mellitus, and 69% (59/86) with insulin use." (PMID 31593545, 2019). "The table also contains specific diabetes rules, such as the 100/85 rule for estimating the insulin sensitivity (also called “correction factor”) or the 400 rule for estimating the insulin-to-carbohydrate ratio." (PMID 31290396, 2019). "Alloxan was used as the inducing agent to induce diabetes mellitus by prompting selective damage of the pancreatic β-cells producing insulin." (PMID 31513755, 2019). "Diabetes mellitus is a group of metabolic diseases characterized by high blood glucose levels (hyperglycemia) and the inability to produce and/or use insulin." (PMID 31719967, 2019). "This table summarises the prescription of non-insulin diabetes medications by average eGFR consistent with stage 3a, 3b, 4 and 5 chronic kidney disease." (PMID 30777033, 2019). "Our primary outcome was the proportion of patients refilling the various non-insulin diabetes medications during the first 90 days after insulin initiation." (PMID 30759121, 2019). "Diabetes stems from the inability of the body to supply sufficient insulin to meet the metabolic demands." (PMID 30850640, 2019). "Type 2 diabetes mellitus (T2DM) is part of the metabolic syndrome characterized by the body's inability to produce or respond to insulin." (PMID 31250990, 2019). "Although numbers were too small to detect potential significant differences, the proportions of family history of diabetes in first-degree relatives and insulin treatment were greater in the the group with GDM recurrence than the group with no recurrence." (PMID 30767767, 2019). "This revealed a progressive increase in insulin and proinsulin levels leading up to diabetes onset, suggestive of worsening β cell function." (PMID 30842440, 2019). "Twenty-one per cent of participants with insulin-treated diabetes who were diagnosed after age 30 met the study criteria for type 1 diabetes." (PMID 30969375, 2019). "The male and female diabetes patients who received oral agents and insulin injections were the most likely to have depressive symptoms than the diabetes patients with one type of treatment." (PMID 31726788, 2019). "Studies have shown that during diabetes, the activity of Lactate dehydrogenase increase due to impairment in insulin secretion." (PMID 31142215, 2019). "Diabetes develops either because pancreatic β cellsare unable to produce insulin or because peripheral tissues becomeinsulin-resistant." (PMID 31993238, 2019). "The mean (SD) diabetes duration was 8.6 (6.6) years and similar in both arms; 190 patients (23.7%) were receiving insulin treatment." (PMID 31070699, 2019). "Disordered eating, and especially behavior leading to incorrect insulin dosing, is a major hindrance to optimal blood glucose control which is necessary to prevent severe late diabetes complications, and increased mortality." (PMID 30675355, 2019). "Trends in circulating eCBs also recapitulate the symbiotic relationship between obesity and diabetes, as a study of post-menopausal obese women found greater plasma 2-AG levels in insulin-resistant subjects." (PMID 31156558, 2019). "Several studies have suggested that women with diabetes had higher BMI and were more insulin resistant than their men counterparts." (PMID 30668524, 2019). "PTP1B is a clinically relevant treatment target for cancer and diabetes with roles in insulin and EGF signaling and anxiety (48, –, 51)." (PMID 31177093, 2019). "Hyperglycemia, the hallmark of T2DM, has been considered as the link between diabetes and CVD since this association was detected following the institution of insulin treatment in the 1920s." (PMID 30805659, 2019).
diabetes (continued). "The formation of insulin amyloid fibrils in vivo is associated with the clinical syndrome injection-localised amyloidosis, which was observed in diabetes patients after continuous subcutaneous injections of insulin." (PMID 31835741, 2019). "Most of the current drugs for the treatment of diabetes aim to improve insulin production and metabolic regulation." (PMID 31731426, 2019). "In diabetes mellitus, protein tyrosine phosphatases act as negative regulators of insulin signal transduction." (PMID 31783860, 2019). "Most of these publications werebefore 2000, apart from some papers from Ethiopia describing atypicalpresentation of insulin requiring diabetes." (PMID 31673335, 2019). "The tissue expression of vaspin decreased as diabetes worsened, whereas administration of vaspin to obese mice fed with high-fat high-sucrose chow improved glucose tolerance and insulin sensitivity." (PMID 30909620, 2019). "Diabetes and insulin self-administration education must be imparted by health professionals at each follow-up visit." (PMID 31915711, 2019). "Diabetes mellitus (DM) is defined as a group of metabolic diseases characterized by hyperglycemia resulting from defects in insulin secretion, insulin action, or both." (PMID 30962800, 2019). "For those with a known diagnosis of diabetes (n=173), the majority (80.4%) reported taking an oral glucose-lowering medication and 34.7% reported taking insulin." (PMID 31638591, 2019). "Diabetes remission results from improvements in β-cell function, insulin sensitivity and changes within the gut and adipose tissue." (PMID 31608010, 2019). "In the work by Genereux, age, insulin-treated diabetes, hypertension, smoking, elevated biomarkers or ST-segment deviation and lower ejection fraction were more frequent in patients with incomplete revascularization." (PMID 31174280, 2019). "Only rarely insulin is used as first-line treatment in patients diagnosed with severely dysregulated diabetes." (PMID 31189473, 2019). "Anti-insulin B cells are selectively recruited to pancreatic tissue during diabetes progression and upon entry these cells assume a unique CD138int phenotype." (PMID 31444529, 2019). "Higher levels of expression of PEA15 have been reported in both patients with diabetes mellitus type 2 and in euglycemic patients with impaired insulin sensitivity." (PMID 31998361, 2019). "Diabetes mellitus (DM) is a metabolic disorder characterized by high blood glucose levels owing to impaired insulin secretion or insulin resistance." (PMID 31717650, 2019). "Diabetes mellitus (DM) is a metabolic disorder resulting from defects in insulin secretion, insulin action, or both." (PMID 31347930, 2019). "According to IPA, some of these genes were related to insulin-related pathways and T2D signalling, such as type 2 diabetes mellitus signalling." (PMID 31208038, 2019). "Oxidative stress was considered the pathogenesis of diabetes mellitus and its complications, because it plays a key role in insulin resistance and β-cell dysfunction." (PMID 31159173, 2019). "While metformin was commonly continued among commercially insured adults starting insulin, rates of continuation of other non-insulin diabetes medications were also high." (PMID 30759121, 2019). "The same study also identified three genes in the CPT1-glycine network that relate to diabetes and insulin signaling, thus supporting a central role for insulin in body weight maintenance via coordinated regulation of energy storage pathways and ureagenesis." (PMID 31726987, 2019). "This reflects the definition of a diabetic patient within this study: a patient is defined as diabetic, if he had a pHbA1c ratio ≥6.5% or took at least one medication with an active component classified as “A10”, i.e. insulin and other diabetes medications." (PMID 31562371, 2019). "It is possible that the effect of rosiglitazone on influenza infection is dependent on insulin usage and diabetes comorbidity." (PMID 31159430, 2019).
diabetes (continued). "Some diabetes models assessed glucose and insulin dynamics, while relatively few models explained the epidemiology of diabetes." (PMID 31234452, 2019). "An in vivo study performed in streptozotocin-induced diabetic mice with methanolic and aqueous extract showed that aqueous extract had no impact on diabetes induction, while methanolic extract reduced diabetes incidence and preserved normal insulin secretion." (PMID 31575072, 2019). "While glucocorticoids impair both insulin secretion and insulin sensitivity, development of diabetes is primarily characterized by a beta-cell defect, which becomes more obvious in older patients with a positive family history." (PMID 30467627, 2019). "In contrast, patients with type 2 or secondary diabetes received an initial dose of insulin in accordance with the UK recommendations." (PMID 31418117, 2019). "The worldwide increasing prevalence of diabetes (DM), characterized by insulin secretion defect, insulin resistance or both, burdens the public health." (PMID 31237881, 2019). "We propose that SSTR or SGLT2 antagonists should be considered as adjuncts to insulin in diabetes therapy." (PMID 30635569, 2019). "In vivo, SELENOS expression in liver negatively correlated with blood glucose and serum insulin levels in type 2 diabetes mellitus and metabolic syndrome animal models." (PMID 31880214, 2019). "Prolong hyperglycemia in patients with diabetes due to impairment of insulin pathway leads to oxidative stress (atherogenesis) and the subsequent induction of antioxidant mechanisms as a protective measure." (PMID 31372141, 2019). "Diabetes mellitus (DM) is a chronic metabolic syndrome resulting from defects in pancreatic insulin secretion and/or insulin action on target tissues." (PMID 31061679, 2019). "Diabetes management strategies entailed adaptations of nutritional regimens in four studies, while the remainder assessed different insulin regimens and administration routes." (PMID 31261760, 2019). "A potent and robust insulin-induced upregulation of lipocalin-2, a novel protein involved in obesity and diabetes, was also shown in VAT explants, occurring via the activation of both PI3K and MAPK signaling." (PMID 30754657, 2019). "Genistein seems to modulate on diabetes via direct effects on β-cell proliferation, glucose-stimulated insulin secretion, and protection against apoptosis." (PMID 31191707, 2019). "Collateral history obtained from the patient’s family revealed that her diabetes home regimen included insulin glargine 25 units subcutaneously daily, metformin 1000 mg twice daily, glipizide 10 mg daily and empagliflozin 25 mg daily." (PMID 31259114, 2019). "A joint position statement by ACSM and the American Diabetes Association (ADA) claimed that both resistance and aerobic training can improve insulin action, and assist in management of blood glucose, lipids, cardiovascular risk factors, and quality of life." (PMID 30621076, 2019). "Arthroplasty patients with diabetes treated with insulin have also been shown to have higher rates of 30-day readmission, longer LOS, and other renal, respiratory, and cardiac complications." (PMID 35240760, 2019). "Diabetes mellitus is a metabolic disorder characterized by inappropriate hyperglycaemia, which is stimulated by several factors such as inadequate insulin secretion, insulin inaction, and at times, both." (PMID 31546691, 2019). "Differentiated stem cells, encapsulated in ECM, have been used in the production of insulin, opening up a way for the treatment of diabetes." (PMID 31540457, 2019). "Diabetes is a metabolic disorder characterized by high blood glucose levels and decreased insulin secretion or increased insulin resistance." (PMID 30936916, 2019). "Out of the 304individuals with known diabetes, 44 subjects (14.5%) were on insulin therapy, 216 (71.1%) on oral therapy, and 21 (6.9%) on diet." (PMID 31009496, 2019).
diabetes (continued). "Among participants with diabetes (n = 281), 39% were physician-diagnosed, 3.5% were taking insulin, 31% were taking anti-diabetic oral drugs, and 2.5% were taking both." (PMID 31376594, 2019). "Diabetes mellitus is a metabolic disorder characterized by the elevation of blood glucose due to the defects in insulin action, secretion or both (insulin is insufficient or inefficient)." (PMID 31480505, 2019). "Regarding the duration of diabetes, 54 (21.9%) had an insulin treatment history of less than one year and 130 (52.6%) have been laid between one and five years duration." (PMID 31093506, 2019). "This study identified 6 groups among patients ≥75 years with type 2 diabetes by latent profile analysis, based on age at diabetes diagnosis, insulin sensitivity, absolute and residual β-cell function." (PMID 31382941, 2019). "The participants were patients diagnosed with diabetes who were receiving insulin or oral hypoglycemics and who attended the Diabetes Clinic of the General County Hospital Našice, Croatia to receive their treatment." (PMID 31635047, 2019). "The glucose-triggered insulin release makes the GC/SA-PGGA double-layered nanogels a promising approach for diabetes treatment." (PMID 30893913, 2019). "According to care providers, the denial of diabetes and low independence in its management leads to low compliance with medications, insulin, and healthy lifestyles." (PMID 30621675, 2019). "Diabetes is one of the most common metabolic disorders, and is characterized by the inability to secrete/sense insulin and abnormal blood glucose concentration." (PMID 30755634, 2019). "The main therapy for the treatment of diabetes is injectable insulin administered subcutaneously; however, this has various shortfalls." (PMID 31443473, 2019). "Exercise-induced hypoglycemia is common in diabetics using insulin or insulin secretagogues (i.e., glinides and sulfonylureas)." (PMID 31611821, 2019). "This inflammatory activation leads to impaired insulin secretion and function, which further exacerbate diabetes." (PMID 30881587, 2019). "Diabetes mellitus (DM) is a chronic disease characterized by hyperglycemia resulting from defects in insulin secretion, action, or both." (PMID 30845668, 2019). "We show that this mouse produces human insulin, develops insulitis, but is largely protected from diabetes, similarly to Ins1 knock-out NOD mice." (PMID 31821343, 2019). "Currently, Continuous intraperitoneal insulin infusion (CIPII) is used as a last‐resort treatment option for selected patients with type 1 diabetes mellitus (T1DM) who fail to reach glycaemic control despite intensive subcutaneous (SC) insulin therapy." (PMID 31592137, 2019). "The most common precipitating factors for DKA in the developed countries were poor adherence to insulin therapy, infection and newly diagnosed diabetes mellitus." (PMID 31101104, 2019). "In conclusion, we provide new evidence which highlight a high level of clinical inertia regarding insulin initiation in T2D by prescribing diabetes specialist healthcare professionals in Central and South-Eastern Europe." (PMID 30993528, 2019). "The proportion of persons receiving anti-diabetic drug treatment (either oral anti-diabetic drugs, insulin, or both) among those with prevalent diabetes increased in the overall population (p for trend=0.008)." (PMID 31319658, 2019). "Ninety-nine years after the discovery of insulin by Banting and Best, insulin is still the only available therapy for patients with diabetes once β-cell function is fully declined." (PMID 31815004, 2019). "Steroids were used as initial therapy in 3 because of concomitant adrenal insufficiency and insulin was used in 2 to treat diabetes mellitus." (PMID 30693099, 2019). "Three were type 1 PGDM, one of them had twenty years duration of diabetes, a pre-pregnancy HbA1c of 10% and mean HbA1c of 8.67%, and was treated with continuous subcutaneous insulin infusion." (PMID 31776421, 2019).
diabetes (continued). "Patients on insulin therapy (treatment strategy C) were older (median age: 67 years vs 63 or 65 for A and B, respectively) with longer diabetes duration (mean duration: 15.3 years vs 5.2 and 10.1 for A and B, respectively)." (PMID 31023374, 2019). "The myriad of disorders linked with type 2 diabetes mellitus (T2DM) include insulin resistance, impaired glucose homeostasis, and deficiency of insulin resulting from β-cell dysfunction." (PMID 30854019, 2019). "Disturbance in metabolic processes occurring in diabetes mellitus, which is characterised by chronic hyperglycaemia and defects in insulin secretion as well as insulin action, or both, can affect the mineral status in various ways." (PMID 30091069, 2019). "Over 30 million people in the United States have diabetes, and approximately 30% of adults with diabetes take insulin to regulate their blood sugar." (PMID 31368439, 2019). "This raises the issue of optimal management of diabetes at school and overcoming different barriers; limited support at school would deprive children from the needed insulin injections at recess time." (PMID 31355293, 2019). "The first top hubs of Type 1 Diabetes Mellitus and CD networks were insulin (INS) and tumor necrosis factor (TNF), respectively." (PMID 32099612, 2019). "In the Ecuadorian cohort, despite obesity, patients had lower blood glucose, insulin and HOMA-IR values, indicating better insulin sensitivity and had a lower incidence of diabetes than their relatives." (PMID 31939483, 2019). "Diabetes mellitus (DM) is a metabolic disease in which the secretion of insulin by pancreatic beta cells, is impaired or the sensitivity of tissues to insulin is reduced." (PMID 30788280, 2019). "The price of insulin is one aspect of the complex issue of access to treatment and management of diabetes." (PMID 31551632, 2019). "Vitamin D deficiency is involved in central pathogenetic mechanisms of diabetes mellitus; it affects insulin sensitivity and β-cell function." (PMID 31762905, 2019). "Although loss of normal β-cell activity is considered a main factor in diabetes, the mechanism by which tissue hypoxia affects insulin secretion is poorly understood." (PMID 31028268, 2019). "Folic acid is a promising agent for the prevention and treatment of hyperglycaemia and diabetes by reducing homocysteine and regulating insulin resistance and glycaemia." (PMID 31983911, 2019). "The shrub Vaccinium myrtillus, also known as bilberry or European blueberry, typically grows in Europe and its leaves are increasingly used for diabetes treatment prior to marketed insulin availability." (PMID 31658729, 2019). "Impaired insulin stimulated GLUT4 trafficking is associated with reduced cardiac function in many disease states, most notably diabetes." (PMID 31920989, 2019). "The mean duration of diabetes was 8.7 ± 8.2 years, mean HbA1c level 52.2 ± 9.7 mmol/l (6.9 ± 0.9%) and 30 (20%) of the patients used insulin." (PMID 30833988, 2019). "The aqueous extract of P. santalinus ameliorates diabetes mellitus via anti-inflammatory pathways and enhancement of insulin function." (PMID 31579450, 2019). "The β-cells of the pancreas are the sole site of expression of insulin and play an essential role in maintaining glucose homeostasis in humans and β-cell failure leads to diabetes." (PMID 31590432, 2019). "The db/db mice in this study were spontaneous diabetes model mice with increasing plasma insulin and blood glucose from 10 to 14 days after birth." (PMID 30704457, 2019). "A recent in vivo study showed that miR-29b is involved in regulation of glucose balance and insulin secretion through a variety of target genes and influences the pathogenesis of diabetes." (PMID 31737629, 2019). "Another important mechanism is replacing animal protein with plant protein, which has been shown to reduce blood lipids and blood pressure, to lower fasting plasma glucose and fasting insulin levels, and to improve glycemic control in diabetes." (PMID 30813546, 2019).